INS (insulin)
Diseases named in the same sentence as INS in open-access papers (continued):
Sharing a sentence is not in itself a finding about the gene and the disease.
type 2 diabetes (continued). "To investigate the effect of CE on type 2 diabetes in vivo, we further performed oral glucose tolerance tests and insulin tolerance tests in type 2 diabetes model rats administered with CE." (PMID 24551069, 2014). "The results indicate that J. regia aqueous extract favorably affects blood levels of glucose, insulin and HbA1C in type 2 diabetic patients." (PMID 24447826, 2014). "It is important to realize that in routine daily clinical practice there is a considerable delay in initiation of insulin therapy after failure of oral glucose-lowering agents in patients with type 2 diabetes." (PMID 24904529, 2014). "A total of 20.9 % (39/187) were treated for diabetes type 2 before surgery, 30 with oral antidiabetic medication only and 9 with insulin (comment 7, reviewer 2)." (PMID 24744188, 2014). "We have previously demonstrated that NEAT score determined by our original questionnaire is favorably associated with insulin sensitivity, waist circumference, high-density lipoprotein cholesterol (HDL-C), blood pressure in patients with type 2 diabetes." (PMID 25075310, 2014). "The resulting reduction of insulin levels triggered hyperglycemia, effectively mimicking type 1 or late stages of type 2 diabetes." (PMID 25144301, 2014). "Overall, our observations identify MC4-R agonism as a viable target for the treatment of obesity and possibly also the insulin resistance which is a central factor involved in the pathogenesis of type 2 diabetes." (PMID 24204009, 2014). "In this study, we measured glucose- and insulin-related variables and plasma amino acid concentrations in people diagnosed with type 2 diabetes." (PMID 25177913, 2014). "Another study showed that exercise increased insulin sensitivity in both type 2 diabetes and healthy control subjects with the same age, BMI, and initial triglyceride levels." (PMID 24775272, 2014). "Oral hypoglycemic agents was the treatment regimen in 52.40% patients with type 2 diabetes, whereas 30.30% patients were taking a combination of oral hypoglycemic agents and insulin and 17.30% patients were on insulin." (PMID 24559109, 2014). "Activation of SIRT1 was reported to improve glucose homeostasis, increase insulin sensitivity, and improve mitochondrial function in skeletal muscle of rodent models of type 2 diabetes." (PMID 25013446, 2014). "Insulin clearance plays a major role in glucose homeostasis and insulin sensitivity in physiological and/or pathological conditions, such as obesity-induced type 2 diabetes as well as diet-induced obesity." (PMID 25071716, 2014). "Patients with type 2 diabetes with such a degree of a deranged glucose metabolism that they had need for insulin at baseline should reasonably be in need for insulin also during the study period." (PMID 25198347, 2014). "Metformin therapy results in significant improvement in body composition and insulin sensitivity of adults with newly diagnosed type 2 diabetes." (PMID 25247153, 2014). "Pharmacological CPT1 inhibition has been suggested as an effective therapy to improve insulin sensitivity in type 2 diabetes patients for nearly two decades." (PMID 25309812, 2014). "Increased insulin initiation in general practice is an important goal given the increasing prevalence of type 2 diabetes and a relative shortage of specialists." (PMID 24479762, 2014). "Previous research showed that activation of PPARγ is mainly involved in regulating lipid metabolism, insulin sensitivity, and glucose homeostasis and its agonist has been used in the treatment of hyperlipidemia and type 2 diabetes." (PMID 25055851, 2014). "Our results did not support the idea that treatment with insulin glargine in type 2 diabetes leads to a stronger stimulation of the IRs than NPH insulin." (PMID 24904529, 2014). "In type 2 diabetes, compensatory excess synthesis of insulin is able to induce stress, especially in the ER-stress." (PMID 24638142, 2014).
type 2 diabetes (continued). "The evaluation of blood glucose and insulin in HFD-induced obese mice is a strong indicator of obesity-induced type-2 diabetes." (PMID 25053966, 2014). "Such visits were generally related to insulin treatment and thus late in the evolution of type 2 diabetes." (PMID 24555698, 2014). "In this acute intervention study we demonstrated that reducing glucocorticoid action appears to improve insulin sensitivity at a number of sites in patients with Type 2 diabetes." (PMID 25104497, 2014). "The treatment of type 1 diabetes is mainly dependent on exogenous insulin, whereas the treatment of type 2 diabetes often includes biguanides, sulfonylureas, α-glucosidase inhibitors, and other drugs." (PMID 24633252, 2014). "At entry 22.7% patients were receiving treatment for type 2 diabetes by oral hypoglycaemics alone (18.1%) or insulin (4.6%)." (PMID 25361884, 2014). "MiR-486-5p regulates the expression of silent information regulator 1 (SIRT1), and SIRT1 expression is correlated with insulin sensitivity and energy expenditure in type 2 diabetic patients." (PMID 24497980, 2014). "Medication therapy for type 2 diabetes ranges from monotherapy or combination therapy with oral antidiabetic agents to physiologic insulin replacement therapy." (PMID 26237392, 2014). "Insulin-sensitizing effects have been observed with GLP-1 analogues in type 2 diabetic animal models." (PMID 24895641, 2014). "Insulin resistance (IR) together with an impaired insulin secretion does play a role in the pathogenesis of type 2 diabetes." (PMID 25419241, 2014). "Type 2 diabetes (T2D) results from a combination of diminished insulin sensitivity in peripheral tissues and of defective insulin secretion by the pancreatic beta-cell." (PMID 25383781, 2014). "When type 2 diabetes patients suffer from the disease for a long duration, many of them need insulin treatment due to dysfunction of pancreas." (PMID 25750761, 2014). "The objective of this study is to identify determinants of initial treatment change following initiation of non-insulin antihyperglycaemic treatment (OAD) for UK patients with type 2 diabetes." (PMID 25163796, 2014). "Glibenclamide is currently an effective treatment for type 2 diabetes patients with impaired insulin secretion, although its clinical application has been generally superseded by sulphonylureas with shorter half-lives." (PMID 25532126, 2014). "There is increasing evidence to show that LGI/LGL diets have the potential to protect against diabetes type II and improve glycaemic profiles by reducing insulin secretion and protein glycosylation." (PMID 24926525, 2014). "Failure of the beta-cells to release enough insulin is an important factor in the development of type-2 diabetes." (PMID 25105407, 2014). "As far as we know, there is only one previous study on the initiation of insulin therapy in type 2 diabetes patients taking into account the type of hyperglycemia." (PMID 23880900, 2014). "Metformin is the first-line treatment for type II diabetes because of its insulin sensitizing effects." (PMID 24955774, 2014). "Of those with Type 2 diabetes, 231 (71.7%) were prescribed oral agents alone, 12 (3.4%) were diet-controlled and 79 (24.5%) were prescribed insulin." (PMID 24823871, 2014). "Type 2 diabetes was defined as intake of anti-diabetic agents, insulin treatment, fasting glucose concentration of more than 126 mg/dl, or hemoglobin A1c of more than 6.5% at re-examination." (PMID 24502834, 2014). "In islet cells, the stimulation of glucose uptake leads to enhanced insulin secretion and an overall hypoglycaemic effect being the mode of action of these drugs in Type 2 diabetes." (PMID 24731772, 2014). "Elevated fatty acids contribute to the development of type 2 diabetes and affect skeletal muscle insulin sensitivity." (PMID 24962347, 2014). "Type 2 diabetes results from failure of the β-cells to compensate for increased insulin demand due to abnormal levels of metabolic factors." (PMID 25198535, 2014).
type 2 diabetes (continued). "This post-hoc analysis represents the first comparison of GL and premix analog insulin for maintaining long-term insulin therapy in a large population of older patients (≥65 years of age) with type 2 diabetes." (PMID 24092662, 2014). "Type 2 diabetes is preceded by insulin resistance, the impaired ability of tissues to take up and store glucose in response to insulin." (PMID 24533087, 2014). "Metformin is the first-line treatment for most patients with type 2 diabetes, while insulin secretagogues and insulin are usually added on later if needed." (PMID 25419576, 2014). "Type 2 diabetes decreases insulin sensitivity in the brain, insulin transport through the blood–brain barrier, and insulin receptor’s sensitivity, and it alters glucose metabolism and energy utilization." (PMID 25018729, 2014). "Postprandial glucose and glycated hemoglobin significantly reduce in type 2 diabetes patients after administration of Technosphere insulin." (PMID 26556194, 2014). "In severely obese type 2 diabetes patients, gastric bypass surgery (GB) reduces body mass index (BMI) and hemoglobin A1c (HbA1c) and allows reduced doses of insulin and other medications." (PMID 24668543, 2014). "SGLT2 inhibitors represent a novel class of drugs for treatment of type 2 diabetes and exert insulin-independent blood glucose lowering effects through the inhibition of glucose reabsorption and subsequent increase of urinary glucose excretion." (PMID 25344694, 2014). "For example, the development of obesity and insulin signaling in type 2 diabetes is influenced by the PMDS as insulin receptor substrate 1 is inactivated by degradation through this system." (PMID 25414638, 2014). "In contrast, another randomized clinical study involving 180 patients with type 2 diabetes showed that chromium administration (1000 μg/day) for 4 months had beneficial effects on HbA1c, glucose, insulin, and cholesterol variables." (PMID 25160946, 2014). "Among adipokines and hepatokines, adiponectin and fetuin-A were consistently found to predict the incidence of type 2 diabetes, both by regulating insulin sensitivity." (PMID 24643166, 2014). "Recent genetic data have demonstrated that the expression of genes involved in the final steps of insulin secretion is reduced in patients with type-2 diabetes." (PMID 25105407, 2014). "Our data corroborate partly previous reports where GA and the GA/A1c ratios are significantly correlated with insulin secretory function in type 2 diabetic patients." (PMID 25013775, 2014). "Metformin is widely used for the treatment of type II diabetes; it promotes lower blood glucose levels by increasing muscle glucose uptake, decreasing insulin resistance and improving insulin sensitivity." (PMID 24940426, 2014). "Tyrosine phosphorylation is associated with a group of enzymes which are mainly involved in the negative regulation of insulin signaling and intertwined in the insulin resistance, complementary to type 2 diabetes." (PMID 25542373, 2014). "Alloxan, as a cytotoxic agent to the insulin-secreting β cells of the pancreas, effectively induces insulin dependent phenotypes that resemble type 1 diabetes or post-beta cell “burnout” type 2 diabetes." (PMID 24891878, 2014). "The five common pathways are ECM-receptor interaction, focal adhesion, insulin signalling, cell communication, and Type II diabetes mellitus." (PMID 25114931, 2014). "A recent study tested the osteogenic activity of amylin in normal rats, fructose-induced insulin-resistant and streptozotocin-induced type-2 diabetic rats." (PMID 24847313, 2014). "Intermittent fasting leads to a prolonged lifespan and positively affects glucose tolerance, insulin sensitivity and incidence of type 2 diabetes in mice." (PMID 24838678, 2014).
type 2 diabetes (continued). "Physiologically, IRS2 has been shown to play a central role in peripheral insulin signaling and pancreatic beta cell proliferation, as knockout of Irs2 in mice results in resistance to insulin and the development of type 2 diabetes." (PMID 25594065, 2014). "After 6 weeks of fructose feeding, rats reliably exhibited increased fasting plasma glucose, insulin, and triglyceride levels and reduced quantitative insulin sensitivity check index values consistent with type-2 diabetes." (PMID 25127027, 2014). "Protein-Tyrosine Phosphatase1B (PTP1B) is a negative regulator of the insulin signaling pathway and is a potential therapeutic target for treatment of type 2 diabetes, cardiovascular disease, metabolic syndrome and cancer." (PMID 25364621, 2014). "The concomitant rise in obesity and type 2 diabetes has mustered a global effort to understand the links between nutrient overload and insulin resistance to enable new therapies." (PMID 25152047, 2014). "Several epidemiological studies also demonstrated that low early-phase insulin response in OGTT can predict future development of type 2 diabetes." (PMID 24454742, 2014). "Similar to patients under insulin treatment for type 1 or type 2 diabetes, most of the patients we evaluated were completely unaware of hypoglycemia during the test." (PMID 24736741, 2014). "Overnutrition and obesity induce inflammatory responses in peripheral metabolic tissues, which decreases insulin sensitivity in target cells (adipocytes and hepatocytes) and contributes to glucose intolerance and the development of type 2 diabetes." (PMID 24675731, 2014). "As a drug counteracting type 2 diabetes, troglitazone increases insulin sensitivity and glucose tolerance in obese subjects." (PMID 25083916, 2014). "Hypoglycemia, especially in insulin treated patients, is the leading limiting factor in the glycemic management of type 1 and type 2 diabetes." (PMID 24397956, 2014). "As barrier, Psychological resistance to insulin therapy can result from a range of personal viewpoints involving cognitive appraisal and emotional reactions in adults with type 2 diabetes." (PMID 24401490, 2014). "At early stagy of type 2 diabetes, blood insulin level is increased that can stimulate the cleavage and release of the extracellular domain of α-klotho into blood and/or urine." (PMID 25084095, 2014). "Poor glycemic control remains a growing problem in patients with type 1 (T1D) or type 2 diabetes (T2D) despite improvements in insulin formulation, delivery and adjunctive therapies." (PMID 24918447, 2014). "Selection in these countries therefore generally followed the international guidelines; insulin has a central role in type 1 and in later stages of type 2 diabetes." (PMID 25259517, 2014). "It has already been reported that MAGE and SD were significantly higher on-hemodialysis than off-hemodialysis in type 2 diabetic patients treated with insulin therapy." (PMID 25526642, 2014). "Other studies have suggested a close correlation between organic acid production and insulin sensitivity in both type 2 diabetes patients and healthy subjects." (PMID 25302301, 2014). "GLP-1 receptor agonism in human islets promotes insulin release; it has therefore become an increasingly attractive target for the treatment of type 2 diabetes." (PMID 24712679, 2014). "Liver PEPCK is a rate-limiting enzyme for gluconeogenesis, a contributing factor in hyperglycemia of Type-II diabetes, in which insulin resistance prevents the normal dominant down-regulation by insulin of PEPCK expression." (PMID 25299635, 2014). "Our previous study also showed that a segment of type 2 diabetes treated with insulin and with well-controlled HbA1c demonstrated elevated glycemic excursions." (PMID 25530811, 2014). "The impact of an increase in HOMA-IR on the development of type 2 diabetes in Japanese individuals would differ depending on the degree of insulin-secreting ability." (PMID 25166121, 2014).
type 2 diabetes (continued). "Direct evidence of IRS‐1 being the critical site of impaired insulin action in human obesity and type 2 diabetes has been elusive." (PMID 25472611, 2014). "Increased PST plasma levels, correlating with catecholamine levels have been found in insulin resistant states such as gestational diabetes, essential hypertension or type 2 diabetes mellitus." (PMID 24465394, 2014). "The determination of the parameters of glucose metabolism, and in particular peripheral insulin sensitivity, is of great interest to clinicians and researchers interested in the aetiology of type 2 diabetes and the metabolic syndrome." (PMID 24363940, 2013). "Our secondary objective was to examine the relationship between insulin use and mortality in patients with type 2 diabetes." (PMID 23308218, 2013). "We conducted individual in-depth interviews with people with type 2 diabetes who were making decisions about insulin treatment." (PMID 24282518, 2013). "In type 2 diabetic patients, an acute increase in circulating insulin levels during a meal decreases plasma concentrations of IL-6 and other inflammatory cytokines." (PMID 23776669, 2013). "In a network-based study similar to this, APP was identified as a negative regulator of insulin abundance in plasma of mice and a potential link between Alzheimer's disease and type 2 diabetes was suggested." (PMID 24376773, 2013). "In summary, both models of type 1 and type 2 diabetes support the proposal that melatonin and insulin represent an antagonistic relationship." (PMID 23535335, 2013). "The UKPDS trial on the other hand, randomly assigned 4209 patients with newly diagnosed type 2 diabetes to either conventional therapy (dietary restriction) or intensive therapy (sulfonylurea or insulin or in obese subjects metformin)." (PMID 23840207, 2013). "Various clinical studies, using anti-inflammatory drugs to treat type 2 diabetes and even prediabetes, showed improvements in beta-cell function and insulin sensitivity, reducing glucose levels." (PMID 23690772, 2013). "Health status in people with Type 2 diabetes on basal–oral therapy is significantly improved with insulin degludec vs. insulin glargine." (PMID 23199058, 2013). "The stress of obesity and the increased demand for insulin at the time of adolescence explain the largely pubertal and postpubertal onset of type 2 diabetes in children." (PMID 23367493, 2013). "The results showed that serum PEDF was reduced by 15% in newly diagnosed type 2 diabetic patients after insulin therapy." (PMID 24367624, 2013). "Among patients with sepsis, five had type 2 diabetes (three were treated with oral antidiabetic agents alone, one with insulin alone, and one with both)." (PMID 23999826, 2013). "In support of previous studies, our data has shown that better glycemic control through initiation of high-dose insulin analog therapy resulted in decreased plasma protein carbonyl formation in type 2 diabetic patients." (PMID 23577222, 2013). "Increased proinsulin-to-insulin (P/I) ratio is clarified to be one marker of β-cells dysfunction, has been observed in type 2 diabetes." (PMID 23776696, 2013). "A recent report showed 13 weeks of IL1Ra therapy improved glycemic control and the function of the insulin-producing beta cell in patients with type 2 diabetes." (PMID 23941335, 2013). "Type 2 diabetes generally involves defects in both insulin sensitivity and pancreatic β-cell secretory capacity." (PMID 23516412, 2013). "This amylin derivative was initially called symlin and thereafter marketed as pramlintide and is used as an adjunct to insulin in the management of type II diabetes." (PMID 23607096, 2013). "The incretin effect on insulin secretion was investigated in 8 subjects with type 2 diabetes (T2D) and 8 with normal glucose tolerance (NGT), using 25, 75, and 125 g oral glucose tolerance tests (OGTT) and isoglycemic intravenous glucose infusions (IIGI)." (PMID 24019903, 2013).